ATR (ATR checkpoint kinase)
Diseases named in the same sentence as ATR in open-access papers (continued):
Sharing a sentence is not in itself a finding about the gene and the disease.
leukemia (24 papers, 2014 to 2025). A malignant (clonal) hematologic disorder, involving hematopoietic stem cells and characterized by the presence of primitive or atypical myeloid or lymphoid cells in the bone marrow and the blood. "To determine whether SRSF2 mutations are sufficient to sensitize leukemia cells to inhibition of ATR, CHK1, and WEE1, we tested the sensitivity of ten isogenic SRSF2 mutant and four wild-type K562 clones to inhibitors of these kinases." (PMID 41279606, 2025). "To determine whether SRSF2 mutations alone are sufficient to sensitize leukemia cells to ATR/CHK1/WEE1 inhibition, we modeled the mutations in two complementary systems: (i) isogenic human K562 cell lines and (ii) knock-in mouse bone marrow progenitors." (PMID 41279606, 2025). "Another study proposed that nucleotide biosynthetic plasticity in leukemia cells is mediated by both ataxia telangiectasia and Rad3-related protein (ATR) signaling and nucleotide metabolic adaptive mechanisms." (PMID 37248212, 2023). "High APOBEC3A-expressing leukemia cells require the ATR-Chk1 checkpoint for survival, while blocking this pathway causes cell death." (PMID 38021159, 2023). "Although we revealed the connection among DHX9, R-loop, PI3K-AKT, and ATR-Chk1 pathway in MDS/leukemia cell lines, the reciprocal relationship among them needs to be further investigated." (PMID 37305700, 2023). "This has been suggested as a key mechanism underlying Myelodysplastic Syndromes (MDS), a pre-leukemia that has the propensity to rapidly progress to acute myeloid leukemia (AML), thus explaining greater ATR dependency in leukemia than most other cancer types." (PMID 35879727, 2022). "Inhibition of ATR in MLL-rearranged leukemia has therapeutic potential, since in mice where ATR expression is reduced, MLL-ENL AML cells growth is affected." (PMID 34594227, 2021). "Here the authors use metabolomics and proteomics to show that inhibition of ATR reduced the activity of these pathways thus providing a valuable therapeutic target in leukemia." (PMID 28808226, 2017). "Our results provide quantitative insights into alterations of nucleotide biosynthetic pathways induced in leukemia cells by inhibiting ATR and rate-limiting de novo (RNR) and salvage (dCK) enzymes." (PMID 28808226, 2017). "Here we show that ATR inhibition in leukemia cells reduces the output of both de novo and salvage pathways." (PMID 28808226, 2017). "The authors hypothesized and confirmed that dCK was responsible for an important resistance mechanism to ATR inhibition in leukemia, as dCK activity could compensate for ATRi-induced downregulation of RNR." (PMID 37248212, 2023). "However, results of our study demonstrated that inactivation of Chk1 abrogated cytarabine-mediated differentiation, thus further demonstrating importance of ATR/Chk1 pathway in promoting cellular differentiation in leukemia cells." (PMID 35790845, 2022). "Dyskerin is an essential nucleolar protein that can affect the growth of tumors through its related mechanism of rRNA processing in the precursor; the rRNA synthesis inhibitor CX-5461 can induce acute lymphocytes by activating the ATM/ATR pathway, leukemia cells stagnate and die." (PMID 35178347, 2022). "On the contrary, inhibition of the replication stress sensing kinase ataxia telangiectasia and Rad3-related protein (ATR) in leukemia cells down-regulates the activity of RNR and deoxycytidine kinase (dCK), rate-limiting enzymes of respectively the de novo and salvage dNTP synthesis pathways." (PMID 32722390, 2020). "JQ1 and AZD6738 (a specific ATR inhibitor) also synergized to induce apoptosis in leukemia cells." (PMID 30761268, 2019). "Therefore, we aimed to test and compare the effects of JQ1 combined with a specific ATR inhibitor (AZD6738) or with azacitidine in leukemia cells." (PMID 30761268, 2019).
leukemia (continued). "In line with this hypothesis, we found that CHK1 is phosphorylated on the ATR substrate site Ser345-Gln346 in lysates generated from leukemia-infiltrated spleens isolated from TCA animals 12 h following cyclophosphamide challenge, in vivo." (PMID 28751718, 2017). "Thus the functional interplay between alternative nucleotide biosynthetic routes and ATR provides therapeutic opportunities in leukemia and potentially other cancers." (PMID 28808226, 2017). "In support of the role of ATR/Chk1 in DSB repair, inhibition of ATR/Chk1 with VE-821 increased the sensitivity of leukemia cells to DOXO." (PMID 39747659, 2025). "Consistent with their findings, we investigated p-Chk1 expression was diminished in DHX9-depleted MDS/leukemia cells, suggesting that DHX9 maintain ATR-Chk1 activity in response to DNA damage." (PMID 37305700, 2023). "Our results indicate that the BRD4-dependent transcriptional program is a defective pathway in MDS and AML pathogenesis and its inhibition induces apoptosis of leukemia cells, which is enhanced in combination with HMA or an ATR inhibitor." (PMID 30761268, 2019). "Previous study has shown that SETD2-mutant leukemia exhibits reduced phosphorylated ATR, indicating impaired DDR; however, the efficacy of ATM/ATR-i in SETD2-mutant leukemia remains unknown." (PMID 40300107, 2025). "In summary, ABL1 loss may serve as important diagnostic factor predicting more malignant phenotype of AML1-ETO and NUP98-fusions -positive leukemias as well as their unique pharmaceutical vulnerabilities to PI3K, ATR and DNA-PK inhibition." (PMID 36959186, 2023). "On the other hand, ABL1 kinase could become a therapeutic target since imatinib increased the sensitivity of AML1-ETO and NUP98-fusions -positive leukemias to PI3K, ATR and DNA-PK inhibitors." (PMID 36959186, 2023). "Also, in our leukemia model, ERG under-expressed genes included ATM, CHEK1 and ATR, which are key genes in the initiation of homology-dependent DNA repair." (PMID 24504051, 2014).
non-small cell lung carcinoma (24 papers, 2018 to 2026). A group of at least three distinct histological types of lung cancer, including non-small cell squamous cell carcinoma, adenocarcinoma, and large cell carcinoma. "VE-822, Berzosertib, is an ATR inhibitor that inhibits chemotherapy-induced DNA damage in non-small cell lung cancer (NSCLC) cells." (PMID 40729369, 2025). "On the other hand, the mutation status of MUC6 and three other genes (ATR, ERBB3 and KDR) was obtained as a marker for the recurrence of non-small-cell lung cancer (NSCLC) patients." (PMID 37504272, 2023). "Similarly, AZD6738, an orally administered and highly potent ATR inhibitor, is being evaluated in a Phase I clinical trial in combination with paclitaxel for patients with advanced solid tumours and non-small cell lung cancer (NSCLC)." (PMID 40256842, 2025). "It has been reported that combining X-ray radiation and an ATR inhibitor (ATRi) enhanced the effect of radiation in non-small cell lung carcinoma (NSCLC) and that combining ATRi with radiation is more effective than the treatments alone in head and neck squamous cell carcinoma." (PMID 39594759, 2024). "It was further shown that Chk1 and ATR inhibition could induce genotoxic stress response and subsequent apoptosis, especially in small-cell lung cancer cells, whereas non-small cell lung cancer cells exhibited resistance to ATR/Chk1 inhibition." (PMID 37762228, 2023). "Recently, in non-small cell lung cancer cells, the AXL inhibitor BGB324 (Bencentinib) has been shown to induce DNA damage and replication stress indicated by ATR/CHK1 phosphorylation." (PMID 35955805, 2022). "Clinically, berzosertib (ATR inhibitor) has shown promise with topotecan in relapsed neuroendocrine cancers and also improving outcomes with gemcitabine in platinum-resistant HGSOC and Non-Small Cell Lung Cancer (NSCLC) with high TMB/LOH." (PMID 40556667, 2025). "The anticancer mechanisms of AITC in human A549 and H1299 non-small cell lung cancer (NSCLC) cells were reported to be due to S and G2/M cell cycle arrest, γH2AX, FANCD2 foci, and ATM/ATR-mediated checkpoint responses that induced replication stress in NSCLS cells." (PMID 36135016, 2022). "However, stratified analysis revealed that ATR inhibitors achieved favorable objective response rates (ORR) and significantly reduced hazard ratios (HRs) for median progression-free survival (PFS) and overall survival (OS) in non-small cell lung cancer (NSCLC)." (PMID 41409249, 2025).
osteosarcoma (24 papers, 2016 to 2026). A usually aggressive malignant bone-forming mesenchymal neoplasm, predominantly affecting adolescents and young adults. "Overexpression of APOBEC3s was shown to increase responsiveness to targeted ATR (Ataxia Telangiectasia and Rad3-Related) and Chk1/2 (Checkpoint Kinase 1 and 2) inhibitors in acute myeloid leukemia and osteosarcoma cell lines." (PMID 41373684, 2025). "We set out to establish optimal conditions for activating and inhibiting ATR in U-2 OS osteosarcoma cells." (PMID 38880245, 2024). "A sublethal dose of auranofin-induced oxidative DNA damage, followed by a strong DNA damage response activation of the DNA damage kinase Ataxia Telangiectasia and Rad3-related (ATR) in osteosarcoma and breast cancer cells." (PMID 39001381, 2024). "ATR inhibitor: In osteosarcoma models, the presence of ALT rendered cells hypersensitive to ATR inhibition." (PMID 34439779, 2021). "Among them, MLLT3, ATM/ATR, DDX10, CASP1 and BRD4 have been extensively studied and shown to be associated with pathogenesis or clinical outcomes in osteosarcoma." (PMID 37894336, 2023). "These in vitro findings offer support for investigating in vivo the potential of a combination of ATR and RNR inhibitors as a new treatment strategy for osteosarcoma." (PMID 42086507, 2026). "Hydrogen peroxide-induced oxidative DNA damage triggered Chk1 phosphorylation at Ser345 and Ser317 in human osteosarcoma U2OS cells, suggesting the activation of ATR DDR." (PMID 37216274, 2023). "We show that the ATR inhibitors VE822 and AZD6738 can potentiate radiation-induced, cGAS-dependent type I interferon signaling in several cell lines from human osteosarcoma and NSCLC." (PMID 36387237, 2022). "To identify the mechanism involving in Licochalcone A-induced G2/M phase arrest in osteosarcoma cells, we tested the activation of ATM-Chk2 and ATR-Chk1, the primary pathway for activating G2/M checkpoint." (PMID 31269698, 2019). "Surprisingly, thioparib strongly, and in a concentration‐dependent manner, inhibited HR activity in U2OS‐DR‐GFP human osteosarcoma cell lines, as measured by the direct repeat (DR)‐GFP reporter assay, in which the ATR inhibitor VE‐821 was used as a positive control." (PMID 36652375, 2023). "In osteosarcoma cell lines with ALT, selective sensitivity to ATR inhibition has been reported." (PMID 32375866, 2020). "Noteworthy, one of the cell lines from our panel was U2OS, a non-ES osteosarcoma cell line recently identified as being highly sensitive to ATR inhibitors due to its reliance on the ALT pathway for telomere maintenance." (PMID 27577084, 2016). "Notably, combined ATR and PARP inhibition has been reported to destabilize stalled replication forks and exhibit synergistic toxicity to tumour cells, and it may be a potential targeted therapy for high ANGscore osteosarcoma population." (PMID 37386055, 2023). "Contrary to what was observed in osteosarcoma models, our results do not indicate a general hypersensitivity of ALT-positive STS cells when ATR is inhibited." (PMID 32366852, 2020). "Two independent ATR inhibitors (ETP-46464: ATRi hereafter and AZ20) showed higher toxicity for ES cells than for human primary cells or non-ES osteosarcomas, and significantly lower LD50 values than the PARP inhibitor olaparib." (PMID 27577084, 2016).
neuroblastoma (20 papers, 2012 to 2025). Neuroblastoma (NB) is the most common solid, extracranial childhood tumor. "In pre-clinical models of neuroblastoma, inhibiting both Aurora-A and ATR causes massive tumour apoptosis and disease eradication." (PMID 37414143, 2023). "ATM mutation is well documented as a determinant of sensitivity to ATR and a recent study showed that low ATM protein levels were associated with ATR inhibitor cytotoxicity in a panel of neuroblastoma cell lines." (PMID 36077823, 2022). "Here, we demonstrate that novel drugs targeting a protein called ATR can specifically kill a type of high-risk neuroblastoma associated with MYCN expression." (PMID 34944835, 2021). "• ALT neuroblastoma cells exhibit greater resistance to the clinical ATR inhibitor AZD6738 when compared to other subtypes of neuroblastoma." (PMID 40115016, 2025). "WEE1, CHEK1, BRCA1, FANCD2, PARP1, and phosphorylation of CHEK1 and ATR were significantly reduced in TRPM2 deleted neuroblastoma and myeloid leukemia cells after doxorubicin treatment." (PMID 35428820, 2022). "Here, the authors, through a comprehensive proteomics analysis, identify ATR as a potential therapeutic target of neuroblastoma and demonstrate the efficacy of the ATR inhibitor BAY1895344 in combination with the ALK tyrosine kinase inhibitor lorlatinib." (PMID 34819497, 2021). "Further, we show that by targeting ATR in combination with other drugs that cause replication stress, we can increase killing of both high-risk MYCN amplified and non amplified neuroblastoma." (PMID 34944835, 2021). "We show that neuroblastoma cells expressing high levels of MYCN are especially sensitive to ATR inhibition, and that this is due to MYCN-increased RS." (PMID 34944835, 2021). "In MYCN amplified neuroblastoma models, ATR has also been proposed to play a role in resolution of transcription/replication conflicts." (PMID 32375866, 2020). "For example, ATM and ATR activation leads to G2 arrest in JCPyV-infected human neuroblastoma cells and oligodendrocytes." (PMID 22952448, 2012). "If so, a combination of ATM and ATR inhibitors may prove more efficacious against ALT+ neuroblastomas compared to either inhibitor alone." (PMID 35053227, 2022). "Effective combined treatment with an approved PARP inhibitor and other inhibitors of DDR/DNA damage checkpoints proteins, including ATR, CHK1, and DNA-PK, or other combinations, might improve the specific killing of neuroblastomas harboring 11q loss." (PMID 34069817, 2021). "The recent report of successful combined use of AURKA CD inhibitors and ATR inhibitors in MYCN amplified neuroblastoma strengthens the potential value of using compounds disrupting both AURKA activity and the interaction with N-Myc for the treatment of this highly aggressive tumor type." (PMID 34884931, 2021). "Finally, we included probes covering additional genes previously found mutated in neuroblastoma, and with potential relevance for neuroblastoma tumor biology or targeted therapies, including ATM and ATR." (PMID 34442335, 2021). "However, we present data showing that in fact ALT neuroblastoma cells are more resistant to the clinical ATR inhibitor AZD6738 compared to other neuroblastoma subtypes." (PMID 32375866, 2020). "It was reported that JCPyV-infected human neuroblastoma IMR-32 cells accumulate in the G2 phase of the cell cycle by activating ATM- and ATR-mediated checkpoint pathways that form part of the cell’s DNA damage response (DDR)." (PMID 37815349, 2023). "JCPyV LT was shown by others to mediate cell cycle arrest at the G2/M phase in a human neuroblastoma cell line through the activation of DDR checkpoint proteins, ATM, and ATR." (PMID 37815349, 2023). "We have evaluated the clinical ATR inhibitor AZD6738, in a panel of neuroblastoma cell lines and found that in contrast, ALT cell lines are relatively resistant to ATR inhibition in comparison to other neuroblastoma cell lines." (PMID 32375866, 2020).
neuroblastoma (continued). "Hence the idea would be to achieve similar outcomes as dual Aurora-A and ATR inhibition and the profound effect that has on apoptosis of MYCN-amplified neuroblastoma tumours." (PMID 37414143, 2023). "Of note, several studies have further suggested that not all ALT+ cancer cell lines, including neuroblastoma lines, exhibited hypersensitivity to ATR inhibitors." (PMID 35053227, 2022). "Here, we report that human neuroblastoma cell lines engineered to express TrkA/NTRK1 in tightly controlled systems fail to activate the G2/M cell cycle checkpoint upon irradiation, which recapitulates the effects of ATM or ATR inhibition." (PMID 34885133, 2021). "Although disruption of either ATR or CHK1 results in replication fork “collapse” in the S phase, a number of studies have suggested that both inhibitors could have a cancer-specific killing ability, including in neuroblastomas." (PMID 34069817, 2021). "Subsequently, it was reported that ALT+ neuroblastoma cell lines exhibit activation of the ATM pathway, rather than the ATR pathway, and that an ATM inhibitor reverses their chemoresistance against temozolomide + SN-38 (the active metabolite of irinotecan)." (PMID 35053227, 2022).